BAG1 (BAG cochaperone 1)
Diseases named in the same sentence as BAG1 in open-access papers (continued):
Sharing a sentence is not in itself a finding about the gene and the disease.
breast carcinoma (continued). "High expression profiles of each Bag-1 isoform have been observed mostly in estrogen receptor (ER) positive breast tumors and Bag-1L isoform prevents apoptosis via enhanced Bcl-2 expression in the presence of estrogen and trigger resistance phenotype in MCF-7 breast cancer cells." (PMID 34995286, 2022). "We also confirmed in normal (N) and tumor (T) tissues from 8 breast cancer patients that the expression of α-actinin which is a focal adhesion and actin cytoskeleton marker did not change in the presence of Bag-1 expression, even though Akt is still upregulated and phosphorylated in breast cancer." (PMID 34995286, 2022). "However, none of the investigated apoptosis-related proteins (Bcl2, Bax, Bcl-xl, Bag1, FAS, FASL) could be helpful in predicting the response to drug treatment for breast cancer." (PMID 35163777, 2022). "A retrospective analysis of BAG-1 expression in metastatic breast cancer in a prospective randomised phase three study was not included further in this review of early breast cancer, and did not demonstrate a role for BAG-1 in predicting response to chemotherapy in later-stage disease." (PMID 28510570, 2017). "Taken together, these data suggest that BAG-1 may have a prosurvival role in HER2+ cells and further justifies investigating the impact of BAG-1 on the sensitivity of HER2+ cells to trastuzumab and the potential of BAG-1 as a therapeutic target in HER2+ breast cancer." (PMID 26958811, 2016). "Based on our current data and previous findings from our group we hypothesised that using Thio-S or Thio-2 inhibitors of BAG-1 protein-protein interactions in combination with trastuzumab, a first-line treatment for HER2+ breast cancer, would further restrict growth of HER2+ breast cancer cells." (PMID 26958811, 2016). "Differential staining and subcellular localisation of the isoforms have not been investigated in the normal breast or breast cancer and are impaired by the absence of isoform-specific antibodies, all current studies in breast detecting ‘total’ BAG-1 expression." (PMID 19066611, 2009). "There is an emerging picture that BAG-1 expression is frequently altered in a range of human cancers relative to normal cells and a recent report suggests the exciting possibility that BAG-1 expression may have clinical utility as a prognostic marker in early breast cancer." (PMID 12373595, 2002). "However, two papers reported that cytoplasmic BAG-1 expression represented a potential marker of improved survival in early-stage breast cancer patients and nonsmall cell lung cancer patients whilst nuclear BAG-1 expression was not related to the malignant potential." (PMID 12402153, 2002). "Overexpression of all TAP–Bag-1 isoforms increased cell viability and proliferative capacity of MCF-7 breast cancer cells and MCF-12A non-tumorigenic breast epithelial cells, indicating that tagged Bag-1 isoforms were functional." (PMID 34428256, 2021). "All six thermogenes appear to be significantly overexpressed in breast cancer (HSPA1A, HSPA4), gliomas (DNAJB5), ovarian cancers (HSPA4, DNAJB5), pancreatic cancers (HSP90AA1), prostate cancer (HSP90AB1), thymic carcinoma (BAG1, HSP90AA1), and uterine cancers (HSPA4), as compared to normal tissue." (PMID 31814876, 2019).
cyst (30 papers, 2008 to 2025). A sac-like closed membranous structure that may be empty or contain fluid or amorphous material. "High levels of bradyzoite (cyst)-specific BAG1 mRNA were detected in the brains of the control SCID mice with no T cell transfer at both the day of the transfer of CD8+ T cells (Day 0) and seven days after the T cell transfer (Day 7)." (PMID 39682747, 2024). "Initially, we induced bradyzoites during a 3 day period of culture at pH 8.2 in ambient CO2 during which they convert to stages that express BAG1 and develop a cyst wall that stains with Dolichos biflorus lectin (DBL)." (PMID 35075105, 2022). "To determine the impact of ROS on T. gondii stage differentiation, we modulated ROS in SkMCs and evaluated BAG1 expression, parasite proliferation and tissue cyst formation." (PMID 34881198, 2021). "To rule out an effect of differences in expression level of GCaMP6f during differentiation, we measured fluorescence intensities of GCaMP6f and BAG1-mCherry in different parasites within the same cyst." (PMID 34860156, 2021). "As evidenced by laborious and time-consuming histological examinations, cyst-producing (i.e. BAG-1 positive) stages appeared as early as 7 DPI in mice, suggesting that, at least until then, H. hammondi multiplied in the tachyzoite stage." (PMID 33494796, 2021). "These properties make BAG1 an appropriate protein to observe antibody response to tissue cyst originated infection." (PMID 25268351, 2014). "It has been reported that BAG1 facilitates the tissue cyst formation and takes important roles in the formation of immune response against toxoplasmosis." (PMID 25268351, 2014). "We quantified the expression level of the major bradyzoite antigen, BAG1, a low molecular weight heat shock protein and the presence of Dolichos biflorus lectin (DL), a marker that binds to the cyst wall." (PMID 21209930, 2010). "The transcription levels of cst1 in the bag1 knockout strain were consistently lower than in the parental strain, both in early in vitro induction and in mouse brain cysts, indicating a compromised cyst-forming ability." (PMID 39080770, 2024). "We further investigated the underlying reason why the bag1 gene is key to efficient cyst development but is not essential for cyst formation." (PMID 39080770, 2024). "Besides, the decrease in cyst numbers was confirmed by the down-regulation of BAG1 using a real-time PCR assay." (PMID 38014940, 2024). "Dissemination of tachyzoites was analyzed by detection of parasite gDNA in different tissues, while the presence of BAG1 transcript, the canonical marker for tachyzoite to bradyzoite conversion, was analyzed in the brain as the preferred site of cyst formation/localization." (PMID 38912206, 2024). "Our in vitro cyst induction assays and transcriptomics analyses demonstrate that ROCY1 is critical for DBA+ cyst formation and for the induction of multiple well-known bradyzoite-associated transcripts, such as BAG1, LDH2, SAG2C, and SRS35B." (PMID 37770433, 2023). "- Reduced brain cyst burden, BAG1 expression, and cyst viability: Cysts isolated from “P” and “T” groups displayed mutilation in the surface membrane and were less infective. - Lessened histopathological insults in the brain. - “T” was more effective than “P” regimen." (PMID 35284438, 2022). "Reactions were also tested using rabbit serum to BAG1 which label bradyzoites inside the cyst." (PMID 36311681, 2022). "Upon successful bradyzoite induction of transgenic parasites, which was verified by RT-PCR of the bradyzoite-specific BAG1 gene, we observed that the reproduction of tachyzoites was distinctly retarded and that cyst-like structures could be observed under the conditions of the inducible medium." (PMID 30876436, 2019). "For instance, AP2IX-9 acts as a repressor of bradyzoite gene expression by binding cis-regulatory elements such as the BAG1 promoter, while AP2IV-3 functions as an activator, with ap2IV-3 knockout resulting in reduced tissue cyst formation." (PMID 40362164, 2025).
cyst (continued). "Along with BCLA, MORC-depleted parasites concomitantly expressed the bradyzoite (BAG1) canonical marker and showed clear reactivity with Dolichos biflorus lectin (DBA), a specific feature of the cyst wall." (PMID 33557824, 2021). "(E) Schematic illustration of the FNR-mCherry BAG1-EGFP dual fluorescence reporter and leakage of FNR-mCherry from the parasitophorous vacuole (PV) (top) or cyst matrix (bottom) following A23187-induced membrane permeabilization." (PMID 34860156, 2021). "The BAG1 gene is not essential for cyst formation or for the normal function of bradyzoites contained within tissue cysts." (PMID 39080770, 2024). "The transfer of the normal T cells did not induce significant reduction of cyst numbers and BAG1 mRNA levels." (PMID 37868957, 2023). "Since the reactivation of cerebral T. gondii infection is initiated by cyst ruptures that induce proliferation of tachyzoites, a ratio of SAG1 mRNA levels versus BAG1 mRNA levels is a useful indicator of the efficiency of the protective immunity to prevent reactivation of the infection." (PMID 36311799, 2022). "Mice vaccinated with bag1-deletion mutants form significantly fewer cysts, implying that BAG1 is not essential for cyst formation but accelerates the process in vivo." (PMID 36439853, 2022). "Disruption of another bradyzoite marker BAG1 also did not affect bradyzoite gene expression in vitro, nor did it affect cyst formation in vivo as reported in one study." (PMID 29180989, 2017). "Related to BAG1 mRNA, its expression was observed on 32 p.i. and forth in both mouse lineages, being higher in C57BL/6 than in BALB/c chronically-infected mice, and these levels were correlated to cyst-like structures in the brain (r = 0.9328; p = 0.0066)." (PMID 24801069, 2014). "Strain C9 demonstrated a defect in expression of BAG1, but not of cyst wall components reacting with Dolichos biflorus agglutinin, both of which are markers traditionally used to identify bradyzoites." (PMID 21655329, 2011). "Moreover, although BAG1 is not required for cyst formation, it influences the efficiency of cyst formation and can promote the formation of tissue cysts in the body." (PMID 39080770, 2024). "Previous studies have indicated that BAG1 is not essential for cyst formation." (PMID 39080770, 2024). "The BAG1 mRNA levels strongly correlated with the cyst numbers (p = 0.0018), indicating that cerebral BAG1 mRNA levels are an effective indicator for cyst burdens in the brains of these mice with and without the transfer of CD8+ normal and immune T cells." (PMID 37868957, 2023). "Two additional groups of infected SCID mice did not receive any T cells as another control, and cyst numbers and mRNA levels for bradyzoite (cyst)-specific BAG1 in their brains were measured at 1 day before (Day −1) and 7 days after (Day 7) the T-cell transfer." (PMID 37868957, 2023). "In the present study, the diagnostic value of sporozoite specific SporoSAG, bradyzoite specific BAG1 proteins and GRA1 protein expressed by all forms of the parasite have been evaluated ELISA using sera systematically collected from mice administered orally with tissue cyst and oocysts." (PMID 25268351, 2014). "The degree of the decrease in the cyst burden was calculated as the fold decreases in cerebral BAG1 levels in the recipients of the normal T cells and immune T cells from infected WT and Prf1−/− mice in comparison with the mean value of BAG1 mRNA levels in the control mice with no T-cell transfer." (PMID 37868957, 2023). "Disruption of TgPPG gene results in the delay in cyst wall formation and bradyzoite conversion; however, complementation only rescued cyst wall formation measured by the DBA staining, but not bradyzoite differentiation as measured by BAG1 expression." (PMID 24385904, 2013).
colorectal cancer (9 papers, 2002 to 2022). A primary or metastatic malignant neoplasm that affects the colon or rectum. "The aim of our study was to investigate the immunohistochemical staining pattern of BAG-1 protein in patients with colorectal cancer and examine associations of BAG-1 expression with various clinicopathological factors and patient survival." (PMID 12402153, 2002). "In colorectal cancer (CRC) cells, SNRPA1 binds directly to the BCL-2-associated athanogene-1 (BAG-1) mRNA to decrease the expression of its outcome." (PMID 35281041, 2022). "They used MGNs and the mediated plasmid pGPH1/GFP/Neo-Bag-1-homo-825 silencing Bag-1 gene for treating colorectal cancer in vivo and in vitro." (PMID 33922066, 2021). "Herein, we observed that the expression of BAG-1 isoforms is post-transcriptionally regulated in colorectal cancer cells and tumors, and that stabilisation of the rG4 by small molecules ligands reduces the expression of endogenous BAG-1 isoforms." (PMID 31504805, 2019). "The different isoforms of BAG-1 are known to be overexpressed in many different cancers, including colorectal cancer (CRC)." (PMID 31504805, 2019). "We demonstrated a critical role for the rG4 in the control of both cap-dependent and independent translation of the BAG-1 mRNA in colorectal cancer cells." (PMID 31504805, 2019). "Silencing of Bag-1 gene was supposed to down-regulate the expression of C-MYC protein that is clinically important for colorectal cancer." (PMID 29861465, 2018). "The aberrant expression of Bag-1 has been found in breast, lung, cervix, esophagus and colorectal cancers." (PMID 29861465, 2018). "The potent anti-tumor effect makes anti-Bag-1-siRNA as a potential therapeutic for colorectal cancer management." (PMID 29861465, 2018). "We have shown earlier that endogenous BAG-1 enhances the function of NF-κB in colorectal cancer cells." (PMID 19293798, 2009). "In the present study, we used a polyclonal antibody that allowed specific detection of human BAG-1 protein and examined the immunohistochemical staining patterns of BAG-1 protein in patients with colorectal cancer." (PMID 12402153, 2002). "There have been few reports regarding the immunohistochemical staining pattern of BAG-1 in colorectal cancer." (PMID 12402153, 2002). "In summary, we can conclude that nuclear BAG-1 expression is an indicator of malignant potential and is a poor prognostic marker in colorectal carcinoma." (PMID 12402153, 2002). "Indeed, this is the first large-scale retrospective study to assess the prognostic significance of BAG-1 expression in patients with colorectal cancer." (PMID 12402153, 2002). "Therefore, the nuclear expression of BAG-1 was impressively correlated with the malignant potential in colorectal cancer." (PMID 12402153, 2002). "Hence, we used the Catalyzed Signal Amplification system (DAKO Corp.), which is an extremely sensitive immunocytochemical visualisation system to facilitate the accurate determination of the expression of BAG-1 in colorectal cancers." (PMID 12402153, 2002). "As a result, the BAG-1 protein may be immunolocalised to the cytoplasm or nucleus in colorectal cancer cells." (PMID 12402153, 2002). "Despite extensive studies of the function of BAG-1, the exact role of BAG-1 in the carcinogenesis and progression of human colorectal cancers remains unclear." (PMID 12402153, 2002).
melanoma (9 papers, 2002 to 2024). A malignant, usually aggressive tumor composed of atypical, neoplastic melanocytes. "Recently, three ARGs including WIPI1, BAG1 and PEX3 were found to be melanoma diagnostic biomarkers with high AUC values, sensibility and specificity values." (PMID 32003756, 2020). "Noteworthily, BAG1, PEX3, and WIPI1 are all membrane-associated molecules and intracellular vesicles play a key role in melanoma biology." (PMID 30622661, 2018). "BAG1 is a survival promoter in different cancers; WIPI aberrant expression in melanoma cell lines has been reported, and its specific mutations are known in melanoma cell lines." (PMID 30622661, 2018). "The molecular mechanisms underlying the functional interaction of BAG1, PEX3, and WIPI1 with melanoma were investigated with Chilibot analysis." (PMID 30622661, 2018). "The HPA database reports higher survival in BAG1 low-expressing melanoma patients (p = 0.04) and a favorable prognostic value in renal cancer." (PMID 30622661, 2018). "These functions could contribute to the development of distant metastases in malignant tumours since the overexpression of BAG-1 in melanoma cells increases the metastatic potential of these tumour cells." (PMID 12402153, 2002). "A second-round validation performed on the Human Protein Atlas database showed strong differential protein expression for BAG1, PEX3, and WIPI1 in melanoma vs control samples, according to the image analysis of 80 human histological sections." (PMID 30622661, 2018). "In conclusion, the present study highlights 3 genes (BAG1, PEX3, and WIPI1), known to play a key role in autophagy, as novel relevant melanoma markers." (PMID 30622661, 2018). "BAG1, PEX3, and WIPI1 were identified as the best three novel candidates as validated markers in both DNA and protein melanoma samples, while CHMP2B has validated differential expression at the DNA level, not observed at the protein level." (PMID 30622661, 2018). "BAG1 and PEX3 expression was also found significantly reduced in metastatic vs primary melanoma (p = 0.00004 and p = 0.002, respectively), indicating their possible role in the metastatic dissemination phase." (PMID 30622661, 2018). "We conclude that WIPI1 (AUC = 0.99), BAG1 (AUC = 1), and PEX3 (AUC = 0.93) are relevant novel melanoma markers at both gene and protein levels." (PMID 30622661, 2018). "BAG1, CHMP2B, PEX3, and WIPI1 confirm strongly different expression levels in melanoma vs healthy skin in IST Online." (PMID 30622661, 2018). "According to Pubmed searches, ARSA, the arylsulfatase A gene, appears to mediate BAG1, PEX3, and WIPI1 interaction with melanoma." (PMID 30622661, 2018). "We conclude that BAG1, CHMP2B, PEX3, and WIPI1 show a strongly different expression in melanoma vs control biopsies, according to data from 418 patients, and have never been related to melanoma according to Pubmed." (PMID 30622661, 2018). "Interestingly, ARSA (arylsulfatase A) is the only ARG mediating BAG1, PEX3, and WIPI1 relation with melanoma." (PMID 30622661, 2018). "We concluded that the role of BAG1, PEX3, and WIPI1 as potential melanoma markers is novel and their action on melanoma may occur at the intracellular vesicle level via molecular pathways involving other ARGs." (PMID 30622661, 2018).